MYH9 (myosin heavy chain 9)
Diseases named in the same sentence as MYH9 in open-access papers (continued):
Sharing a sentence is not in itself a finding about the gene and the disease.
Usher syndrome type 1 (1 paper, 2014). A syndrome characterized by congenital, bilateral, severe sensorineural hearing loss, abnormalities in the vestibular system, and adolescent-onset retinitis pigmentosa. "In particular, from the prognostic perspective, we can expect successful results of CI in hereditary deafness with mutation of specific genes, such as, GJB2, SLC26A4, mitochondrial mutations, OTOF, Usher syndrome type I, DFNA9 (COCH), and DFNA17 (MYH9)." (PMID 25373420, 2014).
viral hepatitis (1 paper, 2012). An acute or chronic inflammation of the liver parenchyma caused by viruses. "Moreover, the vast majority of our MYH9-RD patients (92.3%) had been tested for B and C viral hepatitis, and all those found positive were excluded from the analysis." (PMID 22558294, 2012).
tumor (132 papers, 2011 to 2026). "While current studies demonstrate that CB can reverse tumor drug resistance associated with MYH9, its applicability is limited to a few cancer types, and further investigation is required to determine its effectiveness in other cancers." (PMID 39149512, 2024). "The first was a minor variant of MYH9 with 9% VAF in the tumor that was missed by ctDNA WES (c.1565del)." (PMID 37878600, 2023). "Simultaneously high expression of ATG9B and MYH9 was closely associated with high risk of tumour lymph node invasion and distant metastasis." (PMID 34131310, 2021). "Immunohistochemical analysis showed that MYH9 expression was significantly higher in ESCC tumor tissues, and the expression levels were associated with lymph node metastasis of ESCC patients." (PMID 32788880, 2020). "Myh9 is overexpressed in many cancers, and its high expression is associated with poor prognosis indicating very aggressive phenotype of the tumor." (PMID 32595503, 2020). "MYH9 as a low frequency mutated gene was found in our study using genomic sequencing data of 104 pairs of ESCC tumor and normal samples from China." (PMID 32788880, 2020). "Let-7f acts as a tumor suppressor to inhibit invasion and metastasis in gastric cancers via direct targeting of the tumor metastasis-associated gene, MYH9." (PMID 32660059, 2020). "Somatic mutations of the LUSC2 tumor were also found in a number of novel driver genes such as Myh9, Kmt2d and Keap1." (PMID 29484121, 2018). "MYH9, 10 and 14 mutant tumors also exhibited mutational inactivation and/or copy loss of commonly altered tumor suppressors CDKN2A (p16), FAT1, or NOTCH1, and infrequently altered TGFβ pathway components, TGF-B-R2 or SMAD4." (PMID 26369831, 2015). "Mutation of TGFβ-R-II or copy loss of Smad4 was observed in one tumor each and implicated as a genomic driver in 2/11 MYH9 mutant tumors, a frequency similar to that for these individual genes in the overall dataset." (PMID 26369831, 2015). "Moreover, association of LINC02820 with MYH9 protein protects MYH9 from proteasomal degradation, thus upregulating MYH9 to promote tumor growth and metastasis in ESCC." (PMID 40416600, 2025). "Importantly, circSLAMF6 deficiency inhibited tumor growth in vivo by regulating the miR-204-5p/MYH9 axis." (PMID 32496549, 2020). "Thus, MYH9 expression may be associated with the acquisition of migration and invasion capabilities of tumor cells, which subsequently results in highly intratumoral lymphovascular invasion, and poorer prognoses in the present study." (PMID 25826333, 2015). "Comprehensive and integrated unraveling the intricate crosstalk and the dynamic molecular regulatory network of KRT19/MYH9 complex in dictating cell properties among different tumor types is of interest and needs further investigation." (PMID 41345704, 2025). "MYH9 is a multifunctional protein involved in cancer cell proliferation and metastasis, acting as either an oncogene or tumour suppressor in a context-dependent manner." (PMID 40456011, 2025).
tumor (continued). "In vivo, xenograft model indicated that knockdown of MYH9 significantly inhibited the PGK1‐mediated tumour growth and the expression of Snail, SOX2 and β‐catenin." (PMID 40534132, 2025). "Both bioluminescence imaging and tumor specimen analysis indicated that MYH9 knockdown suppressed the promotive effect of RGS19 overexpression on tumor growth." (PMID 38825640, 2024). "In contrast, tissue factor pathway inhibitor 2 (TFPI-2), a tumor suppressor, binds to MYH9 and actinin-4 to inhibit the proliferation of breast cancer cells." (PMID 39273383, 2024). "EBV-miR-BART22 increases MYH9 levels via the activation of the PI3K/AKT/c-Jun pathway to induce tumor stemness, metastasis, and resistance to cisplatin." (PMID 39273383, 2024). "Based on prior research findings, in skin, head and neck squamous cell cancers as well as tongue squamous cell cancers, MYH9 has been identified as a tumor suppressor 37-39." (PMID 39440063, 2024). "The mechanisms through which MYH9 contributes to tumor development and its multifaceted roles in the tumorigenic process are also explored." (PMID 39149512, 2024). "Further investigation is required to elucidate the mechanism by which MYH9 affects tumor proliferation, infiltration, and migration." (PMID 39149512, 2024). "Overexpression of MYH9 has a significant impact on tumor clinical staging through multiple mechanisms, resulting in a poorer prognosis." (PMID 39149512, 2024). "Recent studies increasingly demonstrate the involvement of MYH9 in cell growth, proliferation, tumor invasion, metastasis, and other significant roles in cancer." (PMID 39149512, 2024). "This review presents an overview of MYH9’s role in tumors and introduces potential therapeutic targets, aiming to offer novel insights for exploring tumor mechanisms and treatment." (PMID 39149512, 2024). "Based on our data, we suggest that nKIFC1 impairs the tumor suppressor function of MYH9 and facilitates the amplification of Wnt/β-catenin signaling to a greater extent in AA than in EA TNBC cells." (PMID 38902769, 2024). "Our results suggested that in the context of FOI treatment, compared with the vector group, the tumor was significantly enlarged after overexpression of GALNT5, while the tumor growth was significantly inhibited after continued knocking down MYH9." (PMID 39433745, 2024). "As the c-Myc signaling pathway plays a major role in regulating tumor growth, we analyzed the relationship between MYH9 expression and the c-Myc signaling pathway." (PMID 37770914, 2023). "Apical Me‐EBP50 exerts a tumor suppressor function by establishing and maintaining epithelial polarization through modulation of the MYH9‐dependent cytoskeleton network." (PMID 37539980, 2023). "CircNRIP1 affected the miR-186-5p and MYH9 expressions and enhanced tumor progression and tumor glycolysis in gastric cancer." (PMID 38152652, 2023). "Consistently, silencing of MYH9 significantly inhibited tumor growth, angiogenesis, EMT, and β‐catenin expression in animal models that were generated using SAMD9 overexpressing ESCC cells." (PMID 36757050, 2023).
tumor (continued). "MYH9, GNB1, and ALOX12B were negatively associated with the tumor response, which represented biomarkers of poor outcomes, while HSD17B4 was positively associated with the tumor response." (PMID 36612298, 2023). "In our study, MYH9 enriched in angiogenesis and cell-cell junction, indicating its role in tumor progression." (PMID 36612298, 2023). "We found six heterozygous variants predicted to alter splicing; two in DNA repair-associated genes (BRCA1 and BAP1) and four in tumor suppressor genes (ARHGEF10L, ELL, MYH9, and NCOR2)." (PMID 37234870, 2023). "More recently, circSTX6 containing 4–7 exons of syntaxin-6 gene was shown to promote tumor growth and metastasis by sponging miR-449b-5p, which regulates the expression of myosin heavy chain-9 (MYH9) protein." (PMID 37488598, 2023). "These tumor-promoting effects of ACTN1 overexpression were largely counteracted by MYH9 downregulation." (PMID 38057867, 2023). "In contrast, MYH9 was identified as a tumor suppressor in squamous cell cancers of the head and neck." (PMID 37770914, 2023). "Recent research has revealed that MYH9 also plays a role in driving tumor cell migration and invasion." (PMID 37892851, 2023). "Our in vivo experiments further provided support for these findings, as MYH9 depletion in SCC-1cisR cells notably decreased the tumor size, weight, and volume, which had all been increased by ACTN1 overexpression." (PMID 38057867, 2023). "To elucidate the molecular mechanism of TUBB4A/MYH9-mediated tumor progression, we assessed, with DU145 cells, the role of TUBB4A/MYH9 on the GSK3β/β-catenin signaling pathway by immunoblotting analysis." (PMID 35589707, 2022). "Conversely, MYH9 has been reported to act as a tumor suppressor in skin cancer and in head and neck squamous cell cancers." (PMID 35318312, 2022). "MYH9 knockdown and MYH9 inhibitor, Blebbistatin, displayed anti-tumor effects in DLBCL through inhibiting cell proliferation and viability, inducing cell cycle arrest, promoting cell apoptosis, and decreasing cell invasion." (PMID 34743203, 2022). "Further investigation has revealed that CB can powerfully reverse EBV-miR-BART22-induced cisplatin resistance via upregulating MAP2K4 to antagonize Myh9/GSK3β/β-catenin and its downstream tumor stemness and EMT signals in nasopharyngeal carcinoma." (PMID 36237327, 2022). "High Myh9 expression promotes the invasion and metastasis of tumor cells, and CB suppresses tumor invasiveness via inhibiting Myh9 expression." (PMID 36237327, 2022). "Blebbistatin, an MYH9 inhibitor, functioned as a tumor suppressor in multiple cancers and was demonstrated to inhibit DLBCL progression." (PMID 34743203, 2022). "In the initial study, MYH9 was reported as a tumor suppressor participating in the pathogenesis of squamous cell carcinoma 14,15." (PMID 35414777, 2022). "EBV encoding miR-BART22 enhances DDP chemoresistance by targeting MAP2K4 and activating MYH9/GSK3β/β-catenin-mediated tumor stemness pathways." (PMID 35105963, 2022). "Functional studies revealed that FAM222A-AS1 promoted growth and progression of CRC cells in vitro and in vivo by sponging miR-let-7f to promote the expression of MYH9, indicating a tumor-accelerant role in CRC." (PMID 35646686, 2022). "Although the oncogenic function of MYH9 is known in most cancers, there are inconsistencies in reports of its role in tumor suppression." (PMID 36139430, 2022). "In vivo, we tested the function of MYH9 in a xenograft tumor model and our study found transfection of LV-MYH9 into 786-O cells led to significantly increased volume and weight of xenograft tumors." (PMID 35318312, 2022). "In this study, we identified MYH9 as a key tumor promotor in ccRCC by scRNA-seq analysis and bioinformatics analysis." (PMID 35318312, 2022). "Collectively, our results showed the interaction between PTGDS and MYH9 and the anti-tumor effects of MYH9 inhibition in DLBCL." (PMID 34743203, 2022).
tumor (continued). "LncRNA MRPL23-AS1 promotes tumor progression and carcinogenesis in OS by activating Wnt/β-catenin signaling via inhibiting miR-30b and upregulating MYH9." (PMID 34557357, 2021). "MYH9 has been uncovered to be connected with tumor progression, tumor differentiation, lymph node metastasis, and poor prognosis." (PMID 34901459, 2021). "Many studies propose that MYH9 promotes the progression of many tumors, yet extensive investigations have obtained the strongest evidence that it serves as a tumor suppressor." (PMID 33959503, 2021). "Taken together, we highlighted the vital role of ATG9B in tumour metastasis by accelerating the formation of FAs in a MYH9-dependent manner during cell migration." (PMID 34131310, 2021). "Meanwhile, circSLAMF6 and MYH9 (mRNA and protein levels) were distinctly reduced, while miR-204-5p expression was highly expressed in tumor tissues derived from sh-circSLAMF6 group." (PMID 32496549, 2020). "Subsequently, mice injected with MYH9-silenced HCC cells presented decreased tumor formation ability compared with the control HCC cells in an established subcutaneous xenograft mouse model." (PMID 32296025, 2020). "DDX17 is located at 22q12 in close proximity to the tumour suppressor MYH9, potentially explaining its recurrent deletion in tumour cell lines." (PMID 32463358, 2020). "Altogether, these results imply that knocking down MYH9 reverses CRLF1-induced tumor metastasis and EMT in PTC cells." (PMID 32982961, 2020). "Compared with the control group, the subcutaneous xenograft mouse model results showed that animals injected with MYH9-silenced cells displayed reduced tumor burden and reduced Ki67 and PCNA expression levels." (PMID 32296025, 2020). "Next, we analyzed the expression level of MYH9 by immunohistochemical analysis based on tissue microarray including another 57 of ESCC tumor tissues and paired normal tissues." (PMID 32788880, 2020). "Knocking down MYH9 in CRLF1-overexpressing IHH4 cells markedly lowered tumor formation with significantly smaller volumes of tumors reported compared with the cells transfected with siNC." (PMID 32982961, 2020). "The results revealed that conditional Myh9 knockout significantly decreased tumor incidence and prolonged survival of Tff1-/- mice, when compared with the control littermates." (PMID 32685004, 2020). "In gastric and colorectal cancers, MYH9 accelerates tumor development by enhancing their invasion and metastatic ability." (PMID 32982961, 2020). "We demonstrated that CRLF1 interacts with MYH9, promoting tumor proliferation and metastasis by activating ERK/ETV4; therefore, we provide a prospective therapeutic target for the treatment of PTC." (PMID 32982961, 2020). "The abundance of MYH9 was found to be up-regulated in GC tumor tissues compared with normal tissues from TCGA database." (PMID 32496549, 2020). "We found that overexpressing MYH9 reversed the FOXO1-induced inhibition of NPC tumor stemness, migration, and invasion." (PMID 31754475, 2019). "Our studies demonstrated that CB potently induced FOXO1-mediated DDP sensitivity by antagonizing its binding partner MYH9 to modulate tumor stemness in NPC." (PMID 31754475, 2019). "We demonstrate that FOXO1/MYH9 is a key suppressor of tumor stemness and EMT, thus inducing DPP chemosensitivity in NPC cells." (PMID 31754475, 2019). "This is consistent with previous reports that both MYH9 and MYH10 are overexpressed in several tumors and linked to bad prognosis of these tumor patients." (PMID 29439719, 2018). "MYH9 expression was also observed in fibroblasts in the tumor stroma and in normal bronchial epithelial cells." (PMID 25826333, 2015). "In the present study, MYH9 staining was detected in both the membrane and cytoplasm of some tumor cells, although the staining intensity was markedly stronger in the cell membrane." (PMID 25826333, 2015). "In the present study, MYH9 expression was significantly correlated with poorer tumor differentiation." (PMID 25826333, 2015).